CRP (C-reactive protein)
Diseases named in the same sentence as CRP in open-access papers (continued):
Sharing a sentence is not in itself a finding about the gene and the disease.
osteosarcoma (19 papers, 2014 to 2025). A usually aggressive malignant bone-forming mesenchymal neoplasm, predominantly affecting adolescents and young adults. "Each osteosarcoma sample received a risk score that was determined by CRP and they were then all classified into different risk subgroups based on median value." (PMID 38071320, 2023). "With a meta-analysis conducted through a random-effects model, the pooled results show that elevated CRP is significantly associated with shortening of OS in patients with osteosarcoma (HR = 1.96, 95% CI: 1.28-3.00, P = 0.002; I2 = 60.0%, P = 0.028)." (PMID 34720749, 2021). "These all suggested that CRP is a risk factor for the prognosis of osteosarcoma." (PMID 34720749, 2021). "Additionally, pooled result showed that CRP is significantly associated with shortening of DPS in patients with osteosarcoma (HR = 2.76, 95% CI: 2.01-3.80)." (PMID 34720749, 2021). "The results of the current study indicate that elevated neutrophil count, ESR, NLR, as well as elevated levels of CRP and LDH are significantly associated with the presence of metastasis in osteosarcoma patients." (PMID 40926779, 2025). "The univariate analysis results suggested that tumor volume, tumor stage, NLR, PLR, P-CRP and CRP/Alb were factors that affected the prognosis of patients with osteosarcoma, and the differences were statistically significant (P < .05)." (PMID 36107592, 2022). "In the analysis of CRP, enhanced CRP was related to shortened OS in patients with osteosarcoma (HR = 1.39, 95% CI: 1.06-1.83), and patients with other bone cancers encountered the same situation." (PMID 34720749, 2021). "The outcomes of subgroup analysis to NLR and CRP suggested that histology, ethnicity, metastasis, and sample size all have an impact on its prognosis of patients with osteosarcoma." (PMID 34720749, 2021). "Our pooled results also found that elevated levels of CRP are greatly related to the shortening of OS in patients with osteosarcoma (HR = 1.96, 95% CI: 1.28-3.00) which conforms to the outcomes of most researches." (PMID 34720749, 2021). "Among patients suffering from osteosarcoma, increased CRP level was correlated with shortened OS (HR = 1.39, 95% CI: 1.06-1.83, P = 0.016), and patients with bone sarcomas encountered the same situation (HR = 2.78; 95% CI: 1.40-5.49, P = 0.003)." (PMID 34720749, 2021). "The conventionally established prognostic factors for osteosarcoma included C-reactive protein (CRP), Enneking stage, tumor size, metastasis, alkaline phosphatase, lactate dehydrogenase, pathological fractures, etc.." (PMID 32000789, 2020). "In conclusion, the present study indicated that abnormal pretreatment inflammation-based prognostic scores, such as GPS > 0, CRP > 10 mg/L, NLR > 2.57, PLR > 123.5, and LMR ≤ 4.73, were inversely associated with OS in osteosarcoma." (PMID 28008988, 2016). "Combined RR of CRP expression suggested that the raised serum CRP level had an adverse prognostic effect on overall survival of patients with osteosarcoma (n = 397 in 2 studies; RR = 0.35; 95% CI: 0.18–0.68; p = 0.002)." (PMID 24800842, 2014). "The results of this meta-analysis suggest that CRP expression confers a worse prognosis in patients with osteosarcoma." (PMID 24800842, 2014). "The purpose of this study is to perform a meta-analysis and literature review on the role of CRP in osteosarcoma and to assess the potential role of serum CRP as a prognostic factor for patients with osteosarcoma." (PMID 24800842, 2014). "Irrespective of relatively small number of patients, as well as the fact that the analysis was retrospective, the current meta-analysis indicated that the CRP levels can be used as a key indicator of prognosis for osteosarcoma." (PMID 24800842, 2014). "The neutrophil count, ESR, NLR, and the levels of CRP and LDH are significantly associated with metastasis in osteosarcoma, and they may serve as valuable prognostic markers." (PMID 40926779, 2025).
osteosarcoma (continued). "The effect of CRP/Alb on the prognosis of osteosarcoma has been reported in the literature." (PMID 36107592, 2022). "Additionally, the pooled results show that CRP is greatly related to the shortening of DPS among patients suffering from osteosarcoma (HR = 2.76, 95% CI: 2.01-3.80, P < 0.0001; I2 = 0.0%, P = 0.549)." (PMID 34720749, 2021). "We noticed that the previous study carried out by Yi, J. H. also evaluated whether the level of CRP was correlated with the outcome of patients with osteosarcoma." (PMID 29668751, 2018). "Among patients with osteosarcoma, increased CRP was correlated with shortened OS (HR = 1.52; 95% CI: 1.10–2.09; P = 0.01) (I2 = 17.8%; P = 0.30), and the same was true for patients with other kinds of bone cancer (HR = 1.87; 95% CI: 1.28–2.75; P = 0.02) (I2 = 76.0%; P = 0.04)." (PMID 29668751, 2018). "Furthermore, CRP has been reported as a prognostic factor for children with Ewing’s sarcoma, chordoma, and osteosarcoma, yet a meta-analysis concluded that higher CRP expression indicates a poorer prognosis in cases with bone neoplasms—except for Asian populations." (PMID 37873776, 2023). "The results indicated that neutrophil (p = 0.01), monocyte (p = 0.033), LDH (p < 0.001), ESR (p < 0.001), CRP (p < 0.001), and NLR (p = 0.012) have a statistically significant correlation with the incidence of metastasis in osteosarcoma patients." (PMID 40926779, 2025). "By evaluating the levels of key systemic inflammatory markers, such as CRP, ESR, NLR, and PLR in osteosarcoma patients, we seek to elucidate their potential role as predictive biomarkers for metastatic disease." (PMID 40926779, 2025). "Similar to CRP, elevated ESR is likely driven by proinflammatory cytokines such as IL-6 and TNF-α, which are known to play a role in osteosarcoma pathogenesis." (PMID 40926779, 2025). "This study aimed to investigate the value of the product of peripheral blood platelet and serum C-reactive protein (P-CRP), an inflammatory indicator, for the prognosis of patients with osteosarcoma." (PMID 36107592, 2022). "The univariate analysis of potential factors affecting the prognosis of osteosarcoma patients showed that tumor volume, tumor stage, surgical method, P-CRP, NLR, and CRP/Alb affected the prognosis of osteosarcoma patients, and the differences were statistically significant (P < .05)." (PMID 36107592, 2022). "Our results indicated that GPS, rather than CRP, was an independently prognostic factor of osteosarcoma." (PMID 28008988, 2016). "The prognostic role of C-reactive protein (CRP) in patients with osteosarcoma is not fully investigated." (PMID 24800842, 2014). "Similarly, the pooled results showed that an enhanced level of CRP was related to reduced OS in patients with osteosarcoma regardless of metastasis." (PMID 34720749, 2021). "Hence, the association between systemic inflammatory marker (e.g., NLR, CRP, LMR, GPS, and PLR) levels and the overall survival of patients with osteosarcoma was explored by a meta-analysis, aiming to assess these biomarkers as prognostic factors for overall survival and disease-specific survival." (PMID 34720749, 2021).
renal carcinoma (19 papers, 2006 to 2025). A carcinoma arising from the epithelium of the renal parenchyma or the renal pelvis. "High CRP levels were associated with increased mortality in 90% of cases, especially among patients with gastrointestinal and renal cancers." (PMID 36076988, 2022). "In conclusion, the combined detection of serum Ang, VEGF, and CRP has a potential diagnostic value for the Chinese medicine antitumor formula in treating patients with advanced renal cancer." (PMID 34950214, 2021). "The combined detection of serum Ang, VEGF, and CRP has high diagnostic value for patients with advanced renal cancer treated with Chinese medicine antitumor formula." (PMID 34950214, 2021). "High serum levels of the acute phase protein C-reactive protein (CRP) are associated with an adverse prognosis in renal cancer." (PMID 32707675, 2020). "Commonly studied inflammatory markers such as CRP, IL-6, TNF-α, and procalcitonin (PCT) have all been associated with cancer-related inflammation CRP, for instance, is recognized as a prognostic marker in multiple malignancies, including pancreatic, breast, gastrointestinal, and renal cancers." (PMID 39594709, 2024). "Furthermore, an elevated C-reactive protein concentration has also been shown to be associated with poor survival, independent of stage and grade, in patients undergoing potentially curative resection for renal cancer." (PMID 17003778, 2006). "The aim of the present study was to investigate the biological context of CRP (i.e., the acute cytokine network response and the acute phase reaction) in a representative cohort of patients with renal cancer." (PMID 32707675, 2020). "The aim of the present study was to examine C-reactive protein, interleukin-6 and interleukin-10 concentrations before and following curative resection of renal cancer." (PMID 17003778, 2006). "The renal cancer patients were grouped according to whether they had evidence of a systemic inflammatory response before nephrectomy (C-reactive protein >10 mg l−1)." (PMID 17003778, 2006). "In this study, the CRP level of patients was improved after treatment, suggesting that the Chinese medicine antitumor formula has certain effects on the treatment of advanced renal cancer, and Ang, VEGF, and CRP can be considered as vital indicators to assess the disease progression in patients." (PMID 34950214, 2021). "Although in our group, CRP did not vary significantly between groups, in the case of other types of urological cancers, such as renal cancer, the situation is different." (PMID 41283275, 2025). "The ratio of C-reactive protein to albumin, named as CRP/Alb ratio (CAR), has been widely used as an indicator to predict the prognosis of cardiovascular events, liver surgery and renal cancer surgery." (PMID 36051706, 2022). "In addition to the systemic inflammatory response, CRP is a biomarker that predicts the outcome of IL-2 or IFN-α immunotherapy and has been considered in the evaluation of patients with renal cancer." (PMID 32974174, 2020). "Thus, high IL6 levels are an additional phenotypic characteristic of the acute phase reaction for renal cancer patients with high CRP levels, whereas variation in the other acute phase cytokine mediators is not reflected by CRP in renal cancer patients." (PMID 32707675, 2020). "A selective combination of C-reactive protein and albumin (termed the modified Glasgow Prognostic Score, mGPS) has been shown to have prognostic value, independent of tumour stage, in lung, gastrointestinal and renal cancers." (PMID 21266974, 2011). "However, the basis of the independent relationship between an elevated C-reactive protein concentration and poor survival in renal cancer is not clear." (PMID 16523196, 2006).
sarcoma (19 papers, 2014 to 2026). A usually aggressive malignant neoplasm of the soft tissue or bone. "In various studies, elevated c-reactive protein (CRP) is associated with inferior survival in patients with sarcomas." (PMID 36765774, 2023). "The observation that inflammation and especially CRP and Hb level are associated with a worse outcome in sarcoma patients has been shown previously." (PMID 36233666, 2022). "They demonstrated a significantly higher risk of recurrence and overall decreased survival rates in sarcomas when higher level of pre-operative CRP and NLR are present." (PMID 35267581, 2022). "Patients with sarcoma may have concurrent morbidity that causes a rise in their CRP; therefore, in our study we excluded patients who had clinical evidence of infection or inflammatory disease." (PMID 36900365, 2023). "Of note, in these sarcoma patients, Hb and CRP were shown to be associated with a worse prognosis." (PMID 36233666, 2022). "Preoperative CRP levels were significantly higher in sarcoma patients compared with leiomyoma patients (26.4 ± 46.8 mg/L vs. 0.4 ± 1.6 mg/L; p < 0.001)." (PMID 41976375, 2026). "Concerning the potential role of CRP, in this discussion, we should mention a meta-analysis performed by Wang at al., from which the author concluded that the correlation between pre-treatment levels of CRP and prognosis was concrete in patients’ sarcomas." (PMID 35804835, 2022). "The ability of the Kattan nomogram to predict sarcoma-specific death was improved when serum CRP was added to established prognostic factors such as age, tumor size, histological grade, histological subtype, tumor depth, and tumor site." (PMID 31272506, 2019). "Undifferentiated sarcomas demonstrated the highest CRP levels." (PMID 41976375, 2026). "Elevated CRP (>5 mg/L) was observed in 53.8% of sarcoma cases versus 2.6% of controls." (PMID 41976375, 2026). "On this regard, it is noteworthy that we recently found that C-reactive protein, a well-known marker of inflammation, highly significantly correlates with a poor prognosis rather than with BM, as also demonstrated in sarcomas." (PMID 34124067, 2021). "The median CRP levels in the carcinoma, sarcoma and haematopoietic/lymphoreticular disease subgroups were 11.57 (range: 0.52‐313.3) mg/L, 27.56 (range: 1‐348) mg/L, and 11.9 (range: 0.5‐243) mg/L, respectively; the CRP level in the dog with the neuroendocrine tumour was 0.9 mg/L." (PMID 30411459, 2019). "We analyzed routinely determined laboratory markers including the blood glucose level, CRP, creatinine, uric acid, natrium, and calcium, as well as GGT, GPT, GOT, LDH, and the occurrence of IIN in sarcoma patients." (PMID 36233666, 2022). "Thus, elevated CRP levels might also represent PD-L1 positivity in malignancies including sarcomas." (PMID 31998420, 2020). "Both pretreatment serum CRP (C-reactive protein) level and ALB (albumin) level have been found to be predictive of survival for multiple malignancies including sarcoma." (PMID 31998420, 2020). "To further validate this observation, we investigated the prognostic role of ALC, Hb, LDH, and CRP in a cohort of 10 sarcoma patients without ifosfamide treatment." (PMID 36233666, 2022). "Sarcoma patients with IIN showed an alteration in several inflammatory markers, including a lower lymphocyte count, hemoglobin levels, and calcium levels, as well as elevated GGT, sodium, and CRP levels." (PMID 36233666, 2022). "Since both of the GPS (Glasgow prognostic score) and CAR (C-reactive protein to albumin ratio) are based on the combination of CRP and ALB, we conducted a meta-analysis to evaluate the prognostic role of these two parameters for sarcoma patients." (PMID 31998420, 2020).
subarachnoid hemorrhage (19 papers, 2012 to 2025). A serious neurological disorder characterized by intracranial hemorrhage into the subarachnoid space. "Apart from that, many serum inflammatory biomarkers, such as CRP and serum interleukin-6, were identified as risk factors for predicting an unfavorable prognosis in subarachnoid hemorrhage." (PMID 40951671, 2025). "In addition, high CRP levels are associated with delayed cerebral ischemia and vasospasm after subarachnoid hemorrhage." (PMID 36079002, 2022). "Serum CRP levels were significantly higher in the subarachnoid hemorrhage (SAH) group compared to the Control group on days 3, 7, and 10, reflecting an acute inflammatory response." (PMID 40004783, 2025). "The purpose of this study was to evaluate the role of C-reactive protein (CRP) in predicting neurological outcomes of patients with subarachnoid hemorrhage (SAH)." (PMID 32220241, 2020). "Furthermore, higher CRP levels are also related to delayed cerebral ischemia and vasospasm after subarachnoid hemorrhage." (PMID 37483455, 2023).
Ventricular arrhythmia (19 papers, 2010 to 2026). "This study found that reduced systolic function of the left ventricle and higher peak CRP levels are associated with endogenous plasma 17β-estradiol in the acute phase of MI, and predicted the risk of early in-hospital ventricular arrhythmia." (PMID 41596617, 2026). "Ventricular arrhythmia incidence is associated with significantly elevated proinflammatory markers such as IL-6 and high-sensitive CRP in implantable cardioverter-defibrillator (ICD) patients with structural heart disease." (PMID 22203916, 2011). "Ventricular arrhythmia (VA) occurrence is associated with significantly elevated proinflammatory markers such as IL-6 and highly sensitive C-reactive protein (hs-CRP) in implantable cardioverter-defibrillator (ICD) patients with structural heart disease." (PMID 20885777, 2010). "Based on the positive correlation between serum CRP levels and ECG parameters, we emphasize the increased susceptibility to ventricular arrhythmias based on autoimmune inflammation." (PMID 39000486, 2024). "Serum levels of CRP have been shown to be increased soon after the occurrence of ventricular arrhythmias in other arrhythmogenic diseases like arrhythmogenic right ventricular dysplasia/cardiomyopathy (ARVD/C)." (PMID 22203916, 2011). "This study is the first to demonstrate that systemic inflammation expressed by high C-reactive protein concentration is a more active process soon after spontaneous ventricular arrhythmia in ARVD/C patients, independently of ventricular rate." (PMID 20885777, 2010). "However, the following safety concerns in the cell-treated group were reported: first a small but significant rise in the CRP, second ventricular arrhythmias were observed in 4 treated patients, and third a higher rate of in-BMS restenosis and de novo lesion was found." (PMID 22046562, 2011). "CRP and IL-6 were found to be independent predictors of symptoms of advanced CAD including the incidence of ventricular arrhythmias." (PMID 32093244, 2020). "Interestingly, a positive correlation has been found between CRP and troponin values and ventricular arrhythmias in AMI, underscoring the potential of CRP as a prognostic indicator in malignant arrythmias and sudden cardiac death after AMI." (PMID 40649166, 2025).